CD163 (CD163 molecule)
Diseases named in the same sentence as CD163 in open-access papers (continued):
Sharing a sentence is not in itself a finding about the gene and the disease.
tumor (continued). "Macrophage traits in tumor cells, such as CD163 expression, are reported in breast cancer and are associated with early tumor recurrence and reduced patient survival." (PMID 28881654, 2017). "We also evaluated associations between absolute counts of CD8+ and CD163+ cells in TC and IM regions with the patients’ histological grade, tumor size, lymph node status and pathological stage." (PMID 28428887, 2017). "High levels of CD163+ TIMs were significantly associated with ER status (p = 0.046) and tumour grade (p = 0.004)." (PMID 28913366, 2017). "In our study, there was a significant association between the level of CD163+ TIMs in metastases in tumour-draining ALNs, prior to NAC and the subsequent pCR following 8 cycles of NAC." (PMID 28913366, 2017). "We evaluated two biologic markers in the tumor microenvironment through immunohistochemical staining and analysis of tumor-associated macrophages expressing CD163 and tumor-infiltrating lymphocytes expressing PD-1." (PMID 28036275, 2017). "High levels of CD163+ TIMs in metastatic deposits in tumour-draining ALNs were significantly associated with a pCR (p = 0.003)." (PMID 28913366, 2017). "We determined PD-L1 expression, numbers of CD3+ T cells, CD20+ B cells, CD68+ monocytes/macrophages, Foxp3+ regulatory T cells and CD163+ tumor-associated macrophages by immunohistochemistry in 103 patients." (PMID 29190964, 2017). "Consistent with these tumor-promoting functions of TAMs, expression of the alternative activation marker CD163 in TAMs from malignancy-associated ascites showed a strong correlation with early relapse of serous ovarian carcinoma after first-line therapy." (PMID 28327095, 2017). "In contrast, M2 cells express CD16 and CD163 and are associated with tissue remodeling and tumor progression." (PMID 27129159, 2016). "In conclusion, the results presented here indicate that a high density of either CD68+ or CD163+ TAMs in the tumor microenvironment of adult cHL is associated with poor survival." (PMID 27745550, 2016). "Taken together, the results of our pooled analysis support that a higher density of either CD68+ or CD163+ TAMs in the tumor microenvironment of adult cHL is associated with a higher risk of worst outcome." (PMID 27745550, 2016). "The results of our meta-analysis indicate an association between increased density of both CD68+ and CD163+ TAMs in the tumor microenvironment of adult cHL and poor outcome." (PMID 27745550, 2016). "We observed a significant correlation between the expression of Sema3A and the number of intratumoral macrophages, especially M2 tumor-associated macrophages (CD163+ macrophages)." (PMID 27351132, 2016). "The expression levels of CD68-positive macrophages (P = 0.009) and CD163-positive macrophages (P = 0.015) in tumor nest was significantly associated with poor prognosis." (PMID 26769084, 2016). "Some studies have indicated that a high density of either CD68+ or CD163+ TAMs in the tumor microenvironment of adult cHL is associated with poorer outcomes." (PMID 27745550, 2016). "And in line with our preclinical findings and previous literature data, CD163-positive cells were mainly located in hypoxic/necrotic areas in tumors, a feature that has itself been linked to tumor aggressiveness." (PMID 26797759, 2016). "CD163+ TAMs are a hallmark of the tumor microenvironment and have been associated with poor prognosis in different types of cancer." (PMID 25871392, 2015). "Clinically, it is difficult to confirm that CD163 expression in tumor tissue is caused by cell fusion because the genetic content of macrophages, cancer cells and any hybrids have the same origin." (PMID 26585897, 2015). "Low density of CD68+ or CD163+ macrophages in four combined areas was closely associated with more frequent low-grade histology and the intestinal type tumor of the Lauren classification." (PMID 26714314, 2015).
tumor (continued). "Our results, by demonstrating a strong association between CD163 + (M2) macrophages and tumor budding, support an EMT-promoting role for M2-macrophages." (PMID 25669968, 2015). "In several human malignant tumors, a proportion of CD163-positive M2 TAMs are closely involved in tumor cell proliferation and associated with a poor prognosis." (PMID 24738052, 2014). "In contrast to M1-like macrophages, M2-like macrophages expressed CD163, a marker frequently described for tumor-associated M2-like macrophages." (PMID 24612598, 2014). "In conclusion, we determined that CD163 is a better marker than CD68 for the enumeration of tumor associated macrophages in the everyday practice of surgical pathology." (PMID 22289504, 2012). "Due to loss of material or low tumor cell content, 121 (84%) samples were annotated for CD163 in TS, 105 (73%) for CD163 in TN and 108 (75%) samples were scored for CD68 in both TS and TN." (PMID 22824040, 2012). "In all of the patient biopsies, CD68-positive tumour-associated macrophages presented a mixed CXCL10 (M1)/CD163 (M2) pattern, expressed CXCR4, GM-CSF and HB-EGF, and some stained positive for CXCL12." (PMID 20946648, 2010). "Notably, KRTCAP2 expression showed a significant positive association with the density of infiltrating CD68+ and CD163+ tumor-associated macrophages (TAMs)." (PMID 41676149, 2026). "TME profiling revealed an "immune-cold" phenotype characterized by low densities of CD4+, CD8+, and FOXP3+ T cells, CD19+ and CD20+ B cells, CD56+ and CD57+ NK cells, and CD163+ tumor-associated macrophages, alongside minimal checkpoint activity and focal fibroblast activation." (PMID 42058215, 2026). "Moreover, tumor-associated macrophages (TAMs), particularly CD163-positive subsets, play a crucial role in tumor progression and immune evasion." (PMID 41602389, 2026). "In contrast, the high-risk group was enriched for CD66b+/MMP9+ (pro-tumor neutrophils), FAP+/collagen IV+ (extracellular-matrix-remodeling fibroblasts) and CD163+/MMP9+ (M2-like tumor-associated macrophages), reflecting distinct tumor microenvironments between the two groups." (PMID 41491099, 2026). "Furthermore, the association between high expression of CD68+CD163+ and diminished survival outcomes highlights the importance of the tumor microenvironment in disease prognosis and therapy." (PMID 40362553, 2025). "Total CD163+ macrophages were positively associated with high tumor malignancy grade." (PMID 41150099, 2025). "In contrast, CD68+ and CD163+ cells were positively associated with arginase and negatively associated with nitric oxide, suggesting immune-metabolic patterns commonly observed in the tumor microenvironment." (PMID 41573553, 2025). "Tumor-associated macrophages (TAMs) are characterized as CD11b+CD163+ARG1high cells." (PMID 40806751, 2025). "However, the concurrent enrichment of CD68+CD163+ tumor-associated macrophages and upregulation of macrophage-related signatures indicate a possibly immunosuppressive microenvironment." (PMID 40859352, 2025). "It was suggested that CD163+CD204+ tumor‐associated macrophages could regulate the function and apoptosis of T cell, which suggested that CD163+macrophages influenced the immune regulation and prognosis of the tumor through regulating the T cell function." (PMID 41498045, 2025). "A recent study investigating the spatial distribution and density of immune cell populations in LMUM lesions highlights an enrichment of CD68 + and CD163 + M2-polarized tumor-associated macrophages (TAMs) — a cell type often associated with supporting a pro-tumor microenvironment." (PMID 41160198, 2025). "In addition, the enrichment of CD8+ T cells, CD20+ B cells, CD56+ natural killer cells and CD11c+ dendritic cells, and decreased infiltration of CD68+CD163+ tumor-associated macrophages, were only observed in MPR patients after NAIC." (PMID 40295492, 2025). "The study also analyzed the association between tumor CD163 and PD-L1 expression." (PMID 41142606, 2025).
tumor (continued). "The increased infiltration of CD163+ tumor-associated macrophages (TAMs) contributes to an immunosuppressive microenvironment in RT, which could further impair anti-tumor immunity." (PMID 40565027, 2025). "While being a common marker for tumor associated macrophages (TAMs), CD163 may also be expressed on monocytic myeloid-derived suppressor cells (Mo-MDSCs)." (PMID 39751847, 2025). "Interestingly, high T cell infiltration was linked to high CD68+CD163+ macrophage infiltration in both subtypes, suggesting a coordinated role of these immune cells within the tumor microenvironment." (PMID 40601026, 2025). "In addition, a study reported cross-reactivity of commercial CD206 antibodies with CD163 in M2-like tumor-associated macrophages, leading to false-positive signals—a caveat that underscores the need for rigorous antibody validation." (PMID 40933659, 2025). "Similarly, high levels of CD163+ immune cells in the PT stroma associated with higher tumor grade (P = 0.030) and molecular subtype Luminal B and basal-like." (PMID 39751847, 2025). "Finally, T-cytotoxic lymphocytes (CD8+) and tumor-associated macrophages (CD163+) were evaluated in samples with EGFR and KRAS mutations, ALK rearrangements and LUAD with no genetic findings." (PMID 40809430, 2025). "It has been reported that tumor infiltration of CD163‐positive macrophages is associated with shortened PFS after the treatment initiation of immune checkpoint inhibitors in patients with NSCLC, and shortened OS of patients who were diagnosed as having SCLC between 2017 and 2020." (PMID 41187938, 2025). "To further confirm this, we performed immunohistochemical (IHC) staining for the pan-macrophage marker CD68 19, M1-like and M2b-like macrophage markers CD86 20, M2a-like macrophage marker CD206, and M2c-like macrophage marker CD163 21-23 in serial histological sections of EBV-associated tumours." (PMID 39267775, 2024). "The panel consisted of primary antibodies against various immune cells, including CD20+ B cells, CD3+ T cells, CD8+ T cells, CD68+ macrophages (Mø), CD163+ tumor-associated macrophages (TAMs), CD14+ monocytes (M), CD15+ neutrophils (NE), FOXP3+ Treg cells, and the proliferation marker Ki67." (PMID 38164148, 2024). "Thus, targeting tumor-associated macrophage (TAM) polarization through CD163 expression has been suggested as a therapeutic approach for macrophage-dependent diseases, such as infections and malignancies." (PMID 39451197, 2024). "Altogether, the associations of proinflammatory mast cells and CD68+ macrophages with better outcomes after HCC resection, along with antagonistic effect of antiinflammatory CD163+ macrophages, indicate the importance of tumor-associated inflammation as a major mechanism of antitumor immunity." (PMID 38287290, 2024). "Tumor-associated CAMs downregulated CD163 and upregulated CD304 (encoded by NRP1)." (PMID 38123840, 2024). "In conclusion, HOXA9 could potentiate PDAC progression by stimulating CD163 expressed tumor associated macrophages attraction in tumors." (PMID 39462379, 2024). "In non-small cell lung cancer, the abundance of CD163+ TAMs was associated with the tumor stage, invasive size and differentiation, proliferation rate, and the presence of lymph node metastases, with C-reactive protein (CRP) levels being used as a serum marker." (PMID 39451197, 2024). "Indeed, a higher infiltration of CD163+ M2 macrophages in the normal adjacent epithelium as well as a higher infiltration of CD209+ immature DC at the tumor margin were associated with lethal PCa and BCR, respectively." (PMID 38887294, 2024). "However, in melanoma, increased CD163+ tumor-infiltrating macrophages (M2 phenotype) lead to the loss of Melan-A expression, causing pronounced invasive tumor phenotype." (PMID 39769450, 2024).
tumor (continued). "The degree of lipid deregulation was associated with CD163 antibody on tumour-associated macrophages, indicating the deployment of lipid in the peri-tumoural region as a dynamic process of inflammation during tumour progression." (PMID 38409583, 2024). "Interestingly, the higher CD163+ TAM density in the tumor stroma compared to the tumor area was associated with a decreased survival rate, showing a strong tumorigenic function of this subset of TAMs." (PMID 39451197, 2024). "The negative association between MUFA skewness in the peri-tumoural region and the CD163 antibody on tumour-associated macrophages suggests that spatial distribution of MUFA might impact pro-inflammatory activities." (PMID 38409583, 2024). "In addition, the different cell populations found in the T18_IM RB derived stromal cell line were successfully separated using MACS separation for tumor-associated macrophages (CD163 + CD68) and glia (GFAP)." (PMID 39695086, 2024). "By dividing macrophages into three distinct subpopulations based on CD68 and CD163 markers and known biology of tumor associated macrophages, we could assign them to different CNCs that reflect functional difference." (PMID 38575670, 2024). "HOXA9 might attract CD163 expressed tumor associated macrophages (TAM) and could affect PDAC prognosis." (PMID 39462379, 2024). "In addition, 17KO mice had predominantly suppressed CD163 positive cells, a marker of tumor-associated macrophages (TAMs) compared to wild-type mice." (PMID 39272982, 2024). "Moreover, the MRC1+ cells were also CD163+, which is expressed by monocytes and macrophages and found on tumor associated macrophages as well as M2 macrophages." (PMID 38532508, 2024). "Moreover, a positive correlation was observed between the numbers of NT5E+ cells and CD163+ cells in tumor regions, indicating a potential association between increased NT5E expression and the cold TME in PAAD." (PMID 39911580, 2024). "CD163 expression (27%) in PMP tumor cells was associated with poor prognosis." (PMID 37509688, 2023). "This study examined whether the integration of Ring finger protein 43 (RNF43) expression and CD163+ tumor‐associated macrophage (TAM) infiltration in combination with clinical indexes forecast ccRCC patient outcome with relatively high accuracy." (PMID 36097369, 2023). "On the other hand, mRNA expression of Ccl2 (macrophage chemotaxis marker), Cd68 (tumor associated macrophages, TAMs), Cd163 (M2 TAMs) and Foxp3 (regulatory T cells, Tregs) markers was greatly increased in LLC control mice, while this increment was less pronounced in 6-thio-dG-treated mice." (PMID 37085672, 2023). "CD163 (hemoglobin-scavenger receptor) is another recognized surface marker for M2 macrophage, and the high infiltration of CD163+ M2 macrophage in the tumor microenvironment (TME) has been proven to be associated with tumor progression and poor prognosis in various kinds of solid tumors." (PMID 36864443, 2023). "Also, pooled analysis found CD163+ located within the tumour stroma to be associated with poor survival in OSCC patients (HR = 3.56; 95% Cl: [2.33, 5.44]; p < 0.00001)." (PMID 37397243, 2023). "In various solid tumours, PD-L1 expression has been found to be related to the density of certain subtypes of ICs, including CD4+ T helper cells (Ths), CD8+ cytotoxic T cells (CTLs), FOXP3+ regulatory T cells (Tregs), and CD163+ tumour-associated macrophages (TAMs)." (PMID 38175373, 2023). "Among those, MHCII+ CD163− macrophages that differ phenotypically and functionally compared to other tumor-associated macrophages, increase in number together with the first signs of regression suggesting their crucial contribution to initiating the regression process." (PMID 37526660, 2023). "Both CD3 + /CD4 + and CD3 + /CD8 + T-cell as well as CD68 + /CD163 + hot tumours were significantly associated with high PD-L1 expression scores, which might be relevant for therapy of squamous bladder cancer with pembrolizumab." (PMID 36726072, 2023).
tumor (continued). "Expression of MMPs by cancer-associated fibroblasts and mononuclear inflammatory cells is associated with a worse prognosis in BC, and tumor-associated CD163+ and CD68+ macrophages (TAMs) in the tumor stroma are associated with higher stage and invasiveness in BC." (PMID 37046676, 2023). "Similarly, the combination of TREM2 and its ligand not only promotes tumorigenesis, progression, and the high expression of CD163 in tumor-associated macrophages but also amplifies the inflammatory response in the local tumor microenvironment." (PMID 36741909, 2023). "Meanwhile, high infiltration of CD163+ tumor‐associated macrophages (TAMs) has also been reported to be relevant to poor prognosis in ccRCC, and the interaction between ccRCC and TAMs may contribute to tumor progression." (PMID 36097369, 2023). "CD163+ DC-SIGN+ cells could also be found in tumour tissue, indicating that tumour-associated macrophages (TAMs) from patients can express DC-SIGN and distinguish between Fucosylated and Basal tumour cells." (PMID 35017635, 2022). "We found that tumor-associated neutrophils (CD66b) and NK cells (CD56) were more commonly found in primary tumors than in liver metastases, while tumor-associated regulatory T cells (Foxp3), macrophages (CD163) and IFN-γ were more commonly found in liver metastases (p < 0.05)." (PMID 36195882, 2022). "In the tumor setting, CD163+ tumor-associated macrophage, on the other hand, could elicit cancer associated fibroblasts (CAFs) to express CXCL16, which could further expand these fibroblasts in an autocrine manner." (PMID 36405734, 2022). "M2-polarized (CD163+), tumor-associated macrophages (TAMs) promote tumor growth and spread." (PMID 35402268, 2022). "Increased expression of tumour-associated M2 macrophages (CD163 +) could decrease the function of NK cells, DCs, and T cells in these cold tumours." (PMID 35643506, 2022). "CD163, a marker of tumor-associated macrophages, was also elevated in GP1 (FC = 2.55, p = 0.001)." (PMID 35440542, 2022). "Only GrB+ lymphocytes associated with FoxP3+ Tregs and tumor nest CD163+ macrophages." (PMID 36551965, 2022). "Furthermore, EMR1-TC was significantly associated with CD68+ CD163+ tumor-associated macrophages (TAMs), and CRC with a high combined EMR1-TC+CD68+CD163+ score showed worse recurrence-free survival prognosis." (PMID 36551877, 2022). "We have deepened the understanding of the influence of CD163 on CRC prognosis and also the possible effects on 22 types of lymphocytes, tumor purity, immune check-points such as PD-L1, and the potential involvement of CD163 in different CRC-relevant cancer hallmark pathways and biological processes." (PMID 36551651, 2022). "In this study, we examined CD163 expression in normal and cancer tissues using multiple cohorts of patients and investigated how the dysregulation of CD163 was associated with tumor TME and TICs, as well as patient prognosis at the level of transcriptome and proteome." (PMID 36551651, 2022). "CD163 affected 14 hallmark pathways, mainly revolving around inflammatory response and neoplasia." (PMID 36551651, 2022). "To achieve this, we evaluated the number of CD163+ tumor-associated macrophages in our cohort." (PMID 36010856, 2022). "CD163 is a cell-surface glycoprotein that characterizes tumor-associated M2 macrophages." (PMID 36551693, 2022). "Infiltration of macrophages in the microtissues, detected by CD68 and CD163 immunohistochemistry, may be positively associated with a high level of angiogenesis and tumor progression to malignancy." (PMID 35877331, 2022). "In addition, CD163+ tumor associated-macrophages were positively associated with S100A7 and cPLA2 expression in malignant breast cancer patients." (PMID 35135586, 2022). "The CD163+ M2-like phenotype is also associated with tumor stage and grade in patients with BCa." (PMID 34572939, 2021).